KLHL4 (kelch like family member 4)
Synonyms: KIAA1687; DKELCHL; KHL4
Tractability: Small molecule: it belongs to a druggable protein family. PROTAC: ubiquitination databases record sites on it.
Gene: Protein-coding gene on chromosome X (87,517,409 to 87,670,050, forward strand). Ensembl gene ENSG00000102271.
Subcellular location: Cytoplasm, cytoskeleton
Subcellular location (Human Protein Atlas): Microtubules; Primary cilium; Basal body; Centriolar satellite; Centrosome; Cytokinetic bridge; Mitotic spindle
Gene Ontology:
Molecular function: ubiquitin-like ligase-substrate adaptor activity
Biological process: proteasome-mediated ubiquitin-dependent protein catabolic process
Cellular component: cilium; intercellular bridge; microtubule cytoskeleton; mitotic spindle; Cul3-RING ubiquitin ligase complex; cytoplasm; cytoskeleton
Homologues: Orthologues: chimpanzee KLHL4 (99% identical), macaque KLHL4 (99% identical), pig KLHL4 (91% identical), rat Klhl4 (89% identical), mouse Klhl4 (88% identical), tropical clawed frog klhl4 (81% identical), guinea pig KLHL4 (65% identical), zebrafish klhl4 (30% identical). Paralogues in human: KLHL1 (67% identical), KLHL5 (64% identical), KLHL20 (34% identical), KLHL17 (34% identical), KLHL2 (32% identical), KLHL3 (31% identical), KLHL8 (30% identical), KLHL12 (29% identical), KLHL28 (29% identical), KEAP1 (29% identical), KLHL18 (27% identical), IPP (26% identical), and 42 more.
Diseases named in the same sentence as KLHL4 in open-access papers:
KLHL4 is named in the same sentence as 11 diseases in open-access papers, as found by Europe PMC text mining. Sharing a sentence is not in itself a finding about the gene and the disease. The quoted sentences say what the papers report.
breast carcinoma (2 papers, 2015 to 2019). "Also KLHL4 (Kelch like family member 4) was expected to be down-regulated in breast cancer." (PMID 31238876, 2019).
Intellectual disability (1 paper, 2023). "In addition, a novel variant in KLHL4 (p.I287V) in a patient with severe intellectual disability, brain malformations, and craniofacial defects, was not able to support ectodermal differentiation in vitro or in vivo." (PMID 37495603, 2023).
melanoma (1 paper, 2016). A malignant, usually aggressive tumor composed of atypical, neoplastic melanocytes. "Thus, based on the structure-function relationship encoded Kelch_1, this indicates that the rare mutations in melanoma (e.g. KLHL4 G523R) could alter Kelch_1-mediated function as they affect equivalent positions to the canonical KEAP1 hotspot mutations reported in lung cancer." (PMID 26590264, 2016). "Taken together, the observation that mutations in the Kelch_1 domain of KLHL4 align precisely with hotspot mutations in KEAP1, in tandem with a lack of reports of oncogenic mutations in KLHL4 in melanoma, make these mutations an appealing subject for future investigation." (PMID 26590264, 2016).
microcephaly (1 paper, 2024). A congenital or acquired developmental disorder in which the circumference of the head is smaller than normal for the person's age and sex. "Kelch-like family member 4 (KLHL4) on BTAX is associated with fatal and non-fatal disorders of macro/microcephaly, as well as body mass index disorders due to mutations that result in gene expression differences in humans in the nervous system and in cellular metabolism." (PMID 39766766, 2024).
Obesity (1 paper, 2022). Accumulation of substantial excess body fat. "For those 12 genes, six of them (DDO, SEPT9, TMEM45B, RXRα, ZNF395 and AHRR) were previously reported to be implicated in the obesity or related diseases and the rest six were novel (PACRG, LINC00494, KLHL4, DTX1, VCX3A and VSTM1)." (PMID 35568907, 2022).
orofacial cleft (1 paper, 2017). A disorder of facial skeleton that is characterized by cleft lip and/or cleft palate that result in feeding, speech and hearing problems caused by failures during development. "Associations with KLHL4, EFNB1/PJA1, CPXCR1, TBX22, and BCOR were particularly noteworthy because they are involved in syndromes that feature orofacial clefts." (PMID 28877219, 2017).
Sleep apnea (1 paper, 2023). An intermittent cessation of airflow at the mouth and nose during sleep is known as sleep apnea. "The results showed that Lasso regression identified a total of seven genes as the characteristic genes of sleep apnea, which are: C12orf54, FOS, GPR1, OR9A4, MYO5B, RAB39B, KLHL4, as the core genes of follow-up research and construction of prediction models." (PMID 38077447, 2023).
cancer (1 paper, 2018). A tumor composed of atypical neoplastic, often pleomorphic cells that invade other tissues. "Eight of these had decreased expression in cancer (KLHL3, KLHL4, KLHL13, KLHL14, KLHL29, KLHL30, KLHL32, and KLHL33) while four genes (ENC1, KLHL12, KLHL17, and KLHL35) had patterns of up-regulated gene expression." (PMID 30647843, 2018).
KLHL4 also shares sentences with these, for which no sentence is quoted: neurological disease (1 paper); Ritscher-Schinzel syndrome (1); tumor (1).